WIF1 (Wnt inhibitory factor 1)
Diseases named in the same sentence as WIF1 in open-access papers (continued):
Sharing a sentence is not in itself a finding about the gene and the disease.
acute myeloid leukemia (2 papers, 2021 to 2023). Acute myeloid leukemia (AML) is a group of neoplasms arising from precursor cells committed to the myeloid cell-line differentiation. "Furthermore, activation of the Wnt signaling pathway is required for the survival and development of LSCs and has been implicated in aberrant methylation of Wnt antagonists, such as Wnt inhibitory factor 1 (WIF1) and Dickkopf-1 (DKK1) in acute myeloid leukemia." (PMID 37568748, 2023).
benign breast diseases (2 papers, 2013 to 2022). "Finally, WIF1 was excluded because this gene exhibited an abundant methylation rate (25%) in serum samples from benign breast diseases." (PMID 23320751, 2013).
bladder tumors (2 papers, 2012 to 2015). "A CpG in the promoter of the Wnt inhibitory factor-1 (Wif1) gene, a gene silenced by hypermethylation in bladder tumors and other cancers, was methylated 54% of the time in egg-injected mice, 34% in nitrosamine-fed mice, and 7% in control mice." (PMID 26042665, 2015). "The methylation levels of sFRP-2 and Dkk-3 were found to be significant independent predictors of bladder tumors, whereas with sFRP-1, sFRP-5, and Wif-1, a trend towards significance was found as independent predictors." (PMID 22325146, 2012). "Another study demonstrated higher promoter CpG hypermethylation and lower expression of mRNA transcripts for sFRP-1, sFRP-2, sFRP-4, and sFRP-5, Dkk-3, and Wif-1 genes in bladder tumor compared with normal bladder mucosa showing an inverse correlation." (PMID 22325146, 2012).
colon adenocarcinoma (2 papers, 2007 to 2008). "They reported that Wif1 is over-expressed in intestinal adenomas of ApcMin/+ mice and human colon adenocarcinoma cell lines." (PMID 17506908, 2007). "Furthermore, the WIF1 expression was elevated in intestinal adenomas compared with the normal epithelia of ApcMin/+ mice, and was observed in two human colon adenocarcinoma cell lines." (PMID 18542073, 2008).
diabetic retinopathy (2 papers, 2024 to 2025). "Overexpression of Wnt inhibitory factor 1 (WIF1) suppresses the Wnt/β-catenin signaling pathway, reduces the activity of the AMPK/mTOR signaling pathway, and improves the mitochondrial function caused by diabetic retinopathy." (PMID 41469379, 2025).
endometrial cancer (2 papers, 2012 to 2020). Primary or metastatic malignant neoplasm involving the endometrium (mucous membrane that lines the endometrial cavity). "Interestingly, upon reviewing gene expression profiles obtained from progressive and non-progressive endometrial cancer, a number of inhibitors of Wnt/β-catenin signaling were indeed found to be down-regulated in progressive disease (DKK1, DKK4 and WIF1)." (PMID 22295114, 2012).
gallbladder cancer (2 papers, 2020 to 2022). "It has been identified that hypermethylation in the promoter region of the Wnt inhibitory factor 1 (WIF-1) promoter region is crucial in the progression of cholecystitis to gallbladder cancer." (PMID 32140709, 2020).
Hepatic fibrosis (2 papers, 2016 to 2022). The presence of excessive fibrous connective tissue in the liver. "Treatment with dasatinib significantly elevated the hepatic expression level of Wif-1 by 3.09-fold compared to the liver fibrosis group." (PMID 34894966, 2022). "Our findings are consistent with previous research that found WIF1, a Wnt antagonist, can reduce hepatic fibrosis by inhibiting the Wnt/β-catenin pathway." (PMID 34894966, 2022). "For this purpose, we investigated the potential efficacy and mechanisms of dasatinib in the treatment of thioacetamide-induced liver fibrosis in mice through the modulation of miR-378 and miR-17 that can target Wnt-10 and WIF1, respectively, and inhibit the Wnt/β-catenin pathway." (PMID 34894966, 2022). "Furthermore, the impact of the modulation of miR-17 was reflected on the hepatic expression level of WiF-1 that is significantly reduced by 62% in the liver fibrosis group compared to the control group." (PMID 34894966, 2022).
liver cancer (2 papers, 2021). An epithelial or non-epithelial malignant neoplasm that arises from the liver. "In the present study, we revealed that CRBP-1 inhibited the stemness properties of HCC via upregulating WIF1, then suppressed Wnt/β-catenin signaling pathway, which provided a novel therapeutic target for clinical management of liver cancer." (PMID 34775955, 2021).
lung adenocarcinoma (2 papers, 2013 to 2022). A carcinoma that arises from the lung and is characterized by the presence of malignant glandular epithelial cells. "The qPCR analysis of WIF1 and TNKS expression in three cases of human lung adenocarcinoma revealed the expected repression of WIF1 and moderate overexpression of TNKS2 (as compared to adjacent normal lung tissues) in all examined cases, as well as for TNKS1 in 1 of 3 cases." (PMID 23621985, 2013).
lymphoma (2 papers, 2021 to 2022). A malignant (clonal) proliferation of B- lymphocytes or T- lymphocytes which involves the lymph nodes, bone marrow and/or extranodal sites. "We have recently shown that PRMT5 promotes WNT/β‐CATENIN proliferative signalling through transcriptional repression of pathway antagonists, AXIN2 and WIF1, in three different types of lymphoma cells." (PMID 33462997, 2021). "In contrast to our results in the different lymphoma cell types, we found that AXIN1, AXIN2 and WIF1 mRNA levels were elevated in transformed breast epithelial cells." (PMID 33462997, 2021).
melasma (2 papers, 2022). "The hyperpigmented skin of melasma patients expresses high levels of Wnt inhibitory factor-1 (WIF-1) compared with perilesional normal skin." (PMID 36010618, 2022). "The expression of Wnt inhibitory factor-1 (WIF-1) is significantly reduced in melasma lesions compared to healthy normal control tissue." (PMID 35087618, 2022).
mesothelioma (2 papers, 2024 to 2025). A usually malignant and aggressive neoplasm of the mesothelium which is often associated with exposure to asbestos. "A meta‐analysis has further revealed that the APC gene is significantly hypomethylated in mesothelioma, while CDH1, ESR1, miR‐34b/c, PGR, RARβ, SFRP1, and WIF1 are significantly hypermethylated." (PMID 40904706, 2025). "A recent systematic review and quantitative meta-analysis of DNA methylation in mesothelioma found both significantly hypomethylated genes (APC) and hypermethylated genes (CDH1, ESR1, miR34b/c, PGR, RATO, SFRP1, and WIF1)." (PMID 38297314, 2024).
myocardial infarction (2 papers, 2017 to 2022). Gross necrosis of the myocardium, as a result of interruption of the blood supply to the area, as in coronary thrombosis. "We therefore hypothesized that reduced left ventricular function in WIF1 KO animals 4 weeks after myocardial infarction resulted from an altered inflammatory response." (PMID 28774883, 2017). "In addition, WIF1's presence in human heart tissue samples indicates its potential relevance in patients with myocardial infarction." (PMID 28774883, 2017). "Therefore, WIF1 appears to be a promising target for future immunomodulatory approaches to improving healing after myocardial infarction." (PMID 28774883, 2017). "Finally, we investigated WIF1's protective potential in the context of myocardial infarction." (PMID 28774883, 2017). "Furthermore, we and others have demonstrated that a blockade of Wnt ligands with extracellular Wnt inhibitors like WIF1 and SFRP5 also improves the healing process of myocardial infarction by modulating the inflammatory response." (PMID 36293109, 2022). "To date, WIF1 has not been studied in the context of either myocardial infarction or inflammation." (PMID 28774883, 2017).
retinoblastoma (2 papers, 2022 to 2025). A malignant tumor that originates in the nuclear layer of the retina. "Furthermore, WIF1 overexpression might inhibit retinoblastoma progression induced by miR-340 in vitro and in vivo." (PMID 36619866, 2022). "Among the most upregulated genes were KRT5, KRT19, LCN2, SLP1 and S100A9, while GNAT1, PDE6G, WIF1, FRZB, and RHO were among the top downregulated genes in retinoblastoma." (PMID 40395327, 2025).
salivary gland tumors (2 papers, 2017 to 2022). "Of note, our NGS panel has routinely identified HMGA2 translocations with diverse downstream partners e.g., HMGA2::PTPRD, HMGA2::WIF1, and HMGA2::ACTR6 in three recent salivary gland tumors (carcinoma ex pleomorphic adenoma) that characteristically harbor HMGA2 rearrangements." (PMID 35798968, 2022).
systemic sclerosis (2 papers, 2021 to 2025). A chronic disorder, possibly autoimmune, marked by excessive production of collagen which results in hardening and thickening of body tissues. "SFRP2hiPRSS23+WIF1- fibroblasts amplify immune response with a transcription into myofibroblasts in systemic sclerosis." (PMID 40574847, 2025). "In fibroblasts from Systemic sclerosis (SSc) patients, an autoimmune disease characterized by extensive visceral organ and skin fibrosis, expression of Wif-1 is decreased." (PMID 34483931, 2021).
acute kidney injury (1 paper, 2022). Sudden and sustained deterioration of the kidney function characterized by decreased glomerular filtration rate, increased serum creatinine or oliguria. "As WNT is an essential modulator of fibrosis development, we speculated that local production of WIF1 by podocytes might affect WNT pathway tone in proximal tubules and participate in the progression of fibrosis following acute kidney injury." (PMID 35332151, 2022).
alopecia (1 paper, 2019). Hair loss usually from the scalp. "The APCDD1 gene inhibits the WNT signaling pathway (WIF1), ultimately interfering with BMP, Eda, and Notch pathways, and this aberration causes alopecia and hair loss." (PMID 30993080, 2019). "The differential expression of WIF1, PTPRE, HBB, and LMCD1 is associated with hair loss, morphogenesis, and alopecia." (PMID 30993080, 2019).
anorectal malformation (1 paper, 2018). "This study was performed to investigate the expression pattern of Wnt inhibitory factor 1 (Wif1) and β-catenin during anorectal development in normal and anorectal malformation (ARM) embryos and the possible role of Wif1 and β-catenin in the pathogenesis of ARM." (PMID 29507836, 2018).
basal cell carcinoma (1 paper, 2021). A carcinoma involving the basal cells. "It has been shown that the WIF1 protein is secreted by basal cells, accumulates in suprabasal layers, and suppresses proliferation of keratinocytes, cells from which basal cell carcinoma may develop." (PMID 34944004, 2021). "The influence of WIF1 on hedgehog signaling in vertebrates may also be relevant for the pathogenesis of basal cell carcinomas." (PMID 34944004, 2021).
behavioral disorders (1 paper, 2022). "Suppressing Wif1 in OPCs rescues synaptic loss and behavioral disorders in DISC1-Δ3 mice." (PMID 36131044, 2022).
bone tumor (1 paper, 2023). "For instance, WIF1, a marker of osteoblastic differentiation, was upregulated in our bone tumor." (PMID 36673024, 2023).
brain tumors (1 paper, 2010). "Although it is known that WIF-1 is strongly expressed in embryonic mouse brain, its expression in brain tumors has not yet been a matter of investigation." (PMID 20334650, 2010).
cardiac sarcoma (1 paper, 2023). "WIF1 is a marker of osteoblastic differentiation that highlights the specific differentiation lineage of this rare cardiac sarcoma." (PMID 36673024, 2023).
cardiomyopathy (1 paper, 2013). A disease of the heart muscle or myocardium proper. "In summary, we have found that expression of WIF1 is altered in the cardiomyopathy mouse model and that WIF1 was shown to have harmful effects on function and structure of hearts." (PMID 23921644, 2013). "Furthermore, the expression of WIF1 was found to be regulated in the heart of transgenic mice model of cardiomyopathy." (PMID 23921644, 2013). "Overall, WIF1 showed a similar phenotype to the cTnTR141W transgenic mice of cardiomyopathy." (PMID 23921644, 2013). "The results suggest that WIF1 are involved in the development of the heart and may have contrasting different effects on the pathogenesis of cardiomyopathy." (PMID 23921644, 2013). "However, potential effects of WIF1 on heart development, especially on cardiomyopathy have not yet been approached by either in vivo or in vitro studies." (PMID 23921644, 2013).
cervical intraepithelial neoplasia (1 paper, 2016). "In this study, β-catenin and WIF1 expression were analyzed by immunohistochemistry for 196 patients with CC, 39 with cervical intraepithelial neoplasia (CIN), and 41 with normal cervical epithelium (NCE)." (PMID 27843945, 2016).
cervical tumors (1 paper, 2015). "Several human genes that encode functional inhibitors of the Wnt pathway have been reported to be methylated in cervical tumors including WIF1, CDH1, FHIT, APC, the SLIT2/ROBO family and the SRFP family." (PMID 25826459, 2015).
chronic kidney disease (1 paper, 2022). Impairment of the renal function secondary to chronic kidney damage persisting for three or more months. "In addition, we identified WIF1 as a factor secreted by podocytes that may also contribute to tubular dysfunction in chronic kidney disease." (PMID 35332151, 2022).
cognitive decline (1 paper, 2025). "In the DLPFC, WIF1+/VAV3+ astrocytes were more abundant in individuals at Braak stages 4-6; this astrocyte signature has been reported previously in DLPFC, and may mediate tau-driven synaptic loss and cognitive decline." (PMID 40584839, 2025).
cognitive defect (1 paper, 2016). "In addition, WIF1 has also been confirmed to be directly implicated in the myelination process and hippocampal development, abnormal expression of which may be a possible risk for cognitive defect and dementia." (PMID 27716781, 2016).
diabetes (1 paper, 2022). "More importantly, targeted delivery of Wif1 to podocytes prevented the development of glomerular nephropathy in podocyte-specific Cldn5 knockout mice with diabetes." (PMID 35332151, 2022). "In mice harboring podocyte-specific deletion of Wif1, diabetes-induced proteinuria and podocyte injury were substantially exacerbated." (PMID 35332151, 2022). "To assess the potential role of WIF1 in the development of DN, we induced diabetes by UNX combined with repeated STZ injections." (PMID 35332151, 2022).
diabetic nephropathy (1 paper, 2022). "Systemic delivery of WIF1 suppresses the progression of diabetic nephropathy and ureteral obstruction-induced renal fibrosis." (PMID 35332151, 2022).
diffuse large B-cell lymphoma (1 paper, 2021). "Functional studies, which involved WIF1 gene transfection, were performed only in a diffuse large B-cell lymphoma cell line (i.e. Pfeiffer)." (PMID 33477402, 2021).
dilated cardiomyopathy (1 paper, 2019). Cardiomyopathy which is characterized by dilation and contractile dysfunction of the left and right ventricles. "Wif1 knockout mice show inhibition of Mo differentiation and abnormal chamber remodeling after MI, while un-regulated transgenic WIF1 expression causes dilated cardiomyopathy, collectively indicating that correctly regulated WIF1 positively contributes to cardiac repair." (PMID 30912746, 2019).
endometrioid carcinomas (1 paper, 2018). "In our series, hypermethylation of the Wnt antagonists (DKK1, DKK2, SFRP1, SFRP4, SFRP5, and WIF1) were observed with a significant prevalence in mucinous and endometrioid carcinomas." (PMID 29882921, 2018).
familial cancers (1 paper, 2021).
gastric tumour (1 paper, 2021). "In short, the methylation of ZNF331 and WIF1 we observed was limited to PBLs, which may not be extended to gastric tumour tissues." (PMID 33992091, 2021).
glomerulosclerosis (1 paper, 2022). A hardening of the kidney glomerulus caused by scarring of the blood vessels. "Strikingly, our observations also uncover an important role for Wif1 deficiency in promoting podocyte injury and glomerulosclerosis during DN, and show that systemic administration of Wif1 slightly reduced podocyte injury in a DN model." (PMID 35332151, 2022).
heart failure (1 paper, 2017). Inability of the heart to pump blood at an adequate rate to meet tissue metabolic requirements. "The modules related to the Wnt receptor signaling pathway were limited to heart failure arising from HCM, with increased WIF1 and FRZB." (PMID 29160422, 2017). "Wnt signaling-related treatment may have potential benefits to patients with heart failure arising from HCM, and WIF1 and FRZB may be potential therapeutic targets." (PMID 29160422, 2017).
Hip dysplasia (1 paper, 2024). The presence of developmental dysplasia of the hip. "The expression of WIF1 in the hip capsule of canine hip dysplasia was significantly lower than that in normal tissues." (PMID 39156961, 2024).
Hodgkins lymphoma (1 paper, 2021). A heterogeneous group of malignant lymphoid neoplasms of B-cell origin characterized histologically by the presence of Hodgkin and Reed-Sternberg (HRS) cells in the vast majority of cases. "We have recently reported that elevated levels of PRMT5 up‐regulates WNT/β‐CATENIN proliferative signalling through transcriptional repression of pathway antagonists, AXIN2 and WIF1, in three different types of non‐Hodgkin’s lymphoma cells." (PMID 33462997, 2021).
hypertrophic cardiomyopathy (1 paper, 2013). A condition in which the myocardium is hypertrophied without an obvious cause. "Here, the expression of WIF1 was regulated in a different way in the dilated and hypertrophic cardiomyopathy heart from transgenic mice by mutations in cardiac troponin T, cTnTR141W and cTnTR92Q." (PMID 23921644, 2013).
Insulin resistance (1 paper, 2019). Increased resistance towards insulin, that is, diminished effectiveness of insulin in reducing blood glucose levels. "WNT inhibitory factor 1 (WIF1), FZD7, and ROR2 are novel biomarkers for the development of insulin resistance." (PMID 30678306, 2019).
interstitial cystitis (1 paper, 2025). A rare chronic debilitating urogenital disease characterized by urinary frequency, urgency, and pelvic pain. "There is no existing literature that clarifies the relationship between CCL18, MMP10, and WIF1 with interstitial cystitis." (PMID 40435311, 2025).
intestinal infection (1 paper, 2016). "intestinal infection increases EZH2’s repression of a Wnt-repressive factor, WIF1 (Wnt inhibitory factor 1) coincident with crypt hyperplasia." (PMID 26964089, 2016).
invasive breast carcinoma (1 paper, 2022). A carcinoma that infiltrates the breast parenchyma. "For example, a reduced expression of Wnt-inhibitory factor (WIF1) was seen in 60% of invasive breast carcinomas, and SFRP1 expression, a secreted Wnt antagonist present in breast epithelium, was shown to be lost in 80% of invasive breast carcinomas." (PMID 35663403, 2022).
ischemic cardiomyopathy (1 paper, 2017). Ischemic cardiomyopathy is a cardiomyopathy in which a weakness in the muscle of the heart due to inadequate oxygen delivery to the myocardium with coronary artery disease being the most common cause. "In addition, WIF1 was detected in tissue sections from human patients with acute MI in contrast to patients who were not suffering from cardiac‐related disease or ischemic cardiomyopathy." (PMID 28774883, 2017).
kidney cancer (1 paper, 2014). Primary or metastatic malignant neoplasm involving the kidney. "Wnt inhibitory factor-1 (Wif-1), a sFRP family protein initially identified in the human retina, has been shown to be down-regulated in bladder and kidney cancer, and its expression is inversely correlated with promoter CpG hypermethylation." (PMID 24755523, 2014). "In bladder and kidney cancer, epigenetic promoter CpG hypermethylation of Wif-1 is attributable to its down-regulation." (PMID 24755523, 2014).